E2F1 (E2F transcription factor 1)
Diseases named in the same sentence as E2F1 in open-access papers (continued):
Sharing a sentence is not in itself a finding about the gene and the disease.
hypopharyngeal squamous cell carcinoma (1 paper, 2024). "Targeting the E2F1/SEC61G pathway increased response to chemotherapy in hypopharyngeal squamous cell carcinoma through immune response." (PMID 38689649, 2024).
immune deficiency (1 paper, 2020). "On the other hand, the rare cases with mutations that inactivate PI3Kδ would not lead to an induction of E2F1 expression and tumour formation, while causing immune deficiency." (PMID 32453417, 2020).
infarction (1 paper, 2019). A localised pathological necrosis of tissue resulting from obstruction of the blood supply usually by a thrombus, an embolus, or vascular torsion. "Further investigations are thus warranted to better understand how the interplay between MDM2 and E2F1 impacts myocardial physiology and recovery post-infarction." (PMID 31921839, 2019).
laryngeal carcinoma (1 paper, 2024). Carcinoma that arises from the laryngeal epithelium. "A recent study indicated a downregulation of miR-1205 in laryngeal carcinoma tissue and that this downregulation could be counteracted when E2F1 was overexpressed." (PMID 38827325, 2024).
leprosy (1 paper, 2018). Leprosy is a chronic infectious disease affecting primarily the skin and peripheral nervous system.
Listeria monocytogenes infection (1 paper, 2021). "Finally, we determined that Shigella flexneri or Listeria monocytogenes infection do not affect E2F1 expression, either at early or late times post-infection." (PMID 34099666, 2021).
liver cirrhosis (1 paper, 2022). "Some of the important hub genes in the BisoGenet-derived PPI for liver cirrhosis and HCC diseases were E2F1, TAL1, CEBPB, ELF1, RAD21, CEBPB, and MYC." (PMID 35265561, 2022).
liver disease (1 paper, 2017). "For example, overexpression of E2F1 in a liver disease model of transgenic mice caused dysplasia and tumor formation." (PMID 29312618, 2017).
lymphoid leukemia (1 paper, 2022). A malignant lymphocytic neoplasm of B-cell or T-cell lineage involving primarily the bone marrow and the peripheral blood.
malignant pleural mesothelioma (1 paper, 2016). A malignant neoplasm that arises from mesothelial cells in the pleura and shows a diffuse growth pattern. "Overexpression of miR-223 was capable to block myeloid cell proliferation through E2F1 inhibition and miR-223 was described as a suppressor of cell proliferation in malignant pleural mesothelioma cells through STMN1 targeting." (PMID 27359057, 2016).
medullary thyroid carcinoma (1 paper, 2010). "Additionally, over-expression of IFI16 protein in medullary thyroid carcinoma cells significantly down-regulated the expression of the E2F1, a transcriptional repression target of the pRb-E2F repressor complex." (PMID 20052289, 2010).
metastasis (1 paper, 2024). The spread or migration of cancer cells from one part of the body (where they first appeared) to another. "Moreover, significant findings of E2F2 rs2075993, rs3820028 involvement in LSCC differentiation, and the impact of E2F1 rs3213180 on lymph node metastasis were determined." (PMID 38360622, 2024).
metastatic cancer (1 paper, 2023). A carcinoma which has spread from the original site of growth to another anatomic site. "The retinoblastoma tumor suppressor, pRB, controls cell growth through E2F1-3 transcription factors, and its inactivation drives metastatic cancer, yet its effect on IC modulators is contentious." (PMID 37230983, 2023).
metastatic colorectal cancer (1 paper, 2025). "DDR1 expression is associated with decreased OS in patients with metastatic colorectal cancer, and DDR1 phosphorylation is strongly increased in the corresponding metastatic lesions, indicating that COL4A6 promotes cell invasion via the E2F1/DDR1/FAK axis." (PMID 40603853, 2025).
microcephaly (1 paper, 2024). A congenital or acquired developmental disorder in which the circumference of the head is smaller than normal for the person's age and sex. "Our findings suggested it is unlikely that MCPH1 regulates neurodevelopment through E2F1-mediated transcriptional regulation, and p19ARF-dependent cell cycle arrest and cellular senescence may contribute to the developmental abnormalities observed in primary microcephaly." (PMID 38731817, 2024).
myeloproliferative neoplasm (1 paper, 2021). A clonal hematopoietic stem cell disorder, characterized by proliferation in the bone marrow of one or more of the myeloid (i.e., granulocytic, erythroid, megakaryocytic, and mast cell) lineages. "PRMT5 inhibition was also reported to reduce the expression of E2F targets and alter the methylation status of E2F1 in JAK2V617F-mutant myeloproliferative neoplasms." (PMID 34531375, 2021).
myoepithelial tumor (1 paper, 2022). A benign or malignant tumor characterized by the presence of cells that show myoepithelial differentiation. "In this paper, we analyze the specific gene expression profile induced by SRF gene fusion, focusing on the SRF::E2F1 chimeric transcript that we previously identified in two cases of myoepithelial neoplasms of the soft tissues." (PMID 36421692, 2022). "To confirm that this gene expression signature was present and relevant also in SRF fusion-positive tumors, we analyzed the gene expression profile of two myoepitheliomas carrying SRF::E2F1 chimeric fusion with respect to two EWSR1-rearranged MN." (PMID 36421692, 2022).
Neurodegeneration (1 paper, 2016). Progressive loss of neural cells and tissue. "Other than the potential candidate genes, the compact SPNW also included many significant connecting proteins like APP, BACE1, CCNA2, CREB1, E2F1, EGR1 and MDM2 which were previously implicated to play critical roles in many neurodegeneration disease pathogenesis including Alzheimer’s." (PMID 26784894, 2016).
neuroendocrine lung tumors (1 paper, 2021). "CCNE1 expression is upregulated and correlates with E2F1 status in high-grade neuroendocrine lung tumors." (PMID 33613291, 2021).
neuronal tumor (1 paper, 2012). Neuronal brain tumors are an uncommon group of central nervous system tumors that arise from cells with neuronal differentiation. "Increased expression of the E2F1 transcription factor is found in high risk neuronal tumors and has been proposed as a factor responsible for the initiation step of tumorigenesis." (PMID 23251571, 2012). "In order to understand this seemingly counterintuitive role, we investigated the mechanism by which E2F1 promotes apoptosis in neuronal tumor cells." (PMID 23251571, 2012). "Although E2F1 is over-expressed in most neuronal tumors, studies from many laboratories, including ours, showed that it is also an important mediator of neuronal apoptosis." (PMID 23251571, 2012).
NUT carcinoma (1 paper, 2022). "While JQ1 treatment decreased E2F1 expression in NUT carcinoma cells, no such effect was observed in PCa cells, reinforcing the notion that BET inhibitor resistance in PCa cells is mediated through the mechanism independent of E2F1." (PMID 36274096, 2022).
oesophageal cancer (1 paper, 2021). "Expression of the E2F1 protein in two oesophageal cancer cell lines, ECA109 andTE-13 cells, was detected by Western blot assay." (PMID 33436941, 2021).
Oral leukoplakia (1 paper, 2023). A thickened white patch on the oral mucosa that cannot be rubbed off. "Several pathways were actively enriched, including pathways involved in oral leukoplakia formation, embryonic germ cell pathways, the WNT/β-catenin signaling pathway, and pathways involved in the deregulation of MYC/E2F1 target genes." (PMID 36982384, 2023).
oropharyngeal cancer (1 paper, 2022). Carcinoma, predominantly squamous cell, arising from the epithelial cells of the oropharynx. "A gene polymorphism in the E2F1 promoter region (rs6667575) is associated with HPV16-positive oropharyngeal cancer risk." (PMID 35833075, 2022).
ovarian serous adenocarcinoma (1 paper, 2019). An adenocarcinoma that arises from the ovary and is characterized by the presence of malignant epithelial cells that, in well differentiated tumors, resemble the epithelium of the fallopian tube or, in poorly differentiated tumors, show anaplastic features and marked nuclear atypia. "In Yoshihara's dataset, E2F1 was overexpressed in ovarian serous adenocarcinoma compared with that in the normal samples, with a fold change of 26.734 and p–value of 6.79E-05." (PMID 30967995, 2019).
ovarian serous carcinoma (1 paper, 2019). "In the TCGA dataset, E2F1 was overexpressed in ovarian serous carcinoma compared with that in the normal samples, with a fold change of 1.639 and p–value of 1.29E-06." (PMID 30967995, 2019).
Pca (1 paper, 2020). "Therefore, our study highlights safranal as a potential therapeutic agent for Pca recurrence and provides evidence that pharmacological inactivation of the NF-κB/E2F1–Skp2 axis is a potential therapeutic target against cancer recurrence and progression." (PMID 33392189, 2020).
periodontitis (1 paper, 2023). An acute or chronic inflammatory process that affects the tissues that surround and support the teeth. "In contrast, 8 MRs (ESR1, CEBPB, FOS, BCL6, E2F1, SPI1, STAT3, and ETS1) were consistently expressed at higher levels (U test statistic between 10 and 16) in the periodontitis condition." (PMID 37834287, 2023).
postmenopausal osteoporosis (1 paper, 2022). Metabolic disorder associated with fractures of the femoral neck, vertebrae, and distal forearm. "These insights about metformin will provide clues for future treatment of postmenopausal osteoporosis through modulating E2F1." (PMID 36284303, 2022).
prediabetes (1 paper, 2019). "H3K4me3 was enriched at the promoter of E2F1, LPL, SREBF2, SCD1, PPARG and IL6 in lean normoglycemic compared to morbid obese subjects with prediabetes." (PMID 30958852, 2019).
prostate adenocarcinoma (1 paper, 2020). "We analyzed E2F1 profiling using two public databases (Trento/Cornell/Broad 2016 and the TCGA prostate adenocarcinoma, provisional), and found that E2F1 is either amplified or elevated in a significant portion of patients." (PMID 32354165, 2020). "A Kaplan-Meier survival analysis of the TCGA prostate adenocarcinoma dataset using the UCSC Xena platform indicated a trend of survival disadvantage for patients with high E2F1 expression (top 25%) in comparison to those with low E2F1 expression (bottom 25%)." (PMID 32354165, 2020).
psychosis (1 paper, 2022). "In our opinion, another TF is especially noteworthy: The transcription-activating factor E2F1, also called Retinoblastoma-associated protein 1 (RBAP1), likely binds at CpG m1281, which was hypomethylated in male PWS subjects with a history of psychosis." (PMID 35688807, 2022). "The hypomethylation in PWS males with psychosis seen in our study could thus reflect a dysregulation of proliferation and apoptosis during neurodevelopment caused by lack of Necdin-mediated inhibition of E2F1." (PMID 35688807, 2022).
reflux esophagitis (1 paper, 2017). "In conclusion, our results demonstrated that exosomal miR-29a-3p might assist in the diagnosis of GERD, and increased expression of esophageal miR-223-3p was inversely associated with expression of E2F1 or STAT3 in esophageal tissue reflux esophagitis." (PMID 28757556, 2017).
renal cystic disease (1 paper, 2013).
retinal degeneration (1 paper, 2014). Degeneration of the retina. "MiRNA deregulation is likely not involved in the retinal degeneration phenotype characteristic of Rb loss as both E2f1 TKO and E2f3 TKO retinae show similar patterns of miRNA expression." (PMID 25338120, 2014).
retinal hemangioblastoma (1 paper, 2019). A hemangioblastoma that arises from the retina.
Salmonella Infections (1 paper, 2021). Infections with bacteria of the genus SALMONELLA. "Most importantly, we demonstrated that E2F1 downregulation is triggered by ER-stress response, establishing a causal relationship between induction of ER-stress response in infected/bystander cells and increased Salmonella infection." (PMID 34099666, 2021). "On a global scale, E2F1-dependent miRNAs account for more than 50% of the miRNAs downregulated during Salmonella infection." (PMID 34099666, 2021). "Overall, these results indicate that the transcription factor E2F1 plays a critical role in the regulation of miRNA expression during Salmonella infection." (PMID 34099666, 2021). "Regarding the mechanism of degradation of E2F1 upon Salmonella infection or secretome treatment, we tested the relevance of proteasome degradation to this process." (PMID 34099666, 2021). "In this study, we identified and characterized the transcription factor E2F1 as a major player in the regulation of miRNAs upon Salmonella infection of epithelial cells." (PMID 34099666, 2021). "Together, these results demonstrate that JNK activation mediates the E2F1 regulation during Salmonella infection/secretome treatment." (PMID 34099666, 2021). "Firstly, we determined the kinetics of E2F1 modulation upon Salmonella infection, in samples collected at early (1 and 4 hpi), intermediate (8 hpi), and late stages (20 hpi) of infection." (PMID 34099666, 2021). "Adding to the importance of JNK, we also demonstrate that JNK knockdown prevents the E2F1 downregulation observed during Salmonella infection or secretome treatment." (PMID 34099666, 2021). "We have now determined that E2F1 is a pivotal player in the regulation of the miRNome during Salmonella infection, both in infected and bystander cells." (PMID 34099666, 2021). "We have clearly demonstrated that IRE1 activation is crucial for E2F1 decreased expression during Salmonella infection and secretome treatment (both in IRE1 knockdown cells and cells treated with the IRE1 kinase inhibitor KIRA6)." (PMID 34099666, 2021). "We used a piglet model of Salmonella infection and compared E2F1 expression in mucosal samples of ileum and colon tissues of control or Salmonella-infected animals, collected at 2 and 6 days post-infection." (PMID 34099666, 2021). "Inhibition of the proteasome by MG132 treatment prevented the E2F1 downregulation elicited by Salmonella infection or secretome treatment." (PMID 34099666, 2021). "Salmonella infection elicits a strong decrease of E2F1 expression, which appears to be restricted to this pathogen, not occurring in response to infection by other intracellular pathogens (Shigella flexneri and Listeria monocytogenes)." (PMID 34099666, 2021). "Of note, miRNA independent effects of E2F1 downregulation may also contribute to the observed increase of Salmonella infection." (PMID 34099666, 2021). "Indeed, E2F1 knockdown increased Salmonella infection, specifically the bacterial invasion (1 hpi) and replication (20 hpi), compared to cells transfected with control siRNA." (PMID 34099666, 2021). "Overall, these results demonstrate that the secretome of Salmonella-infected cells is sufficient to elicit E2F1 and miRNA downregulation of naive cells, explaining a major fraction of the miRNA regulation observed in bystander cells during Salmonella infection." (PMID 34099666, 2021). "Collectively, this work reveals that the downregulation of E2F1 and consequently of miRNAs promotes infection, by promoting on one hand the bacterial replication within infected cells as well as by priming bystander cells for efficient Salmonella infection." (PMID 34099666, 2021). "The net effect of E2F1 and miRNA downregulation resulting in increased Salmonella infection is likely explained by the fact that several of these miRNAs have been shown to counteract Salmonella infection." (PMID 34099666, 2021).
Salmonella Infections (continued). "In summary, we demonstrate that downregulation of the transcription factor E2F1 and consequent miRNome changes are crucial for Salmonella infection, by promoting Salmonella replication in infected cells and priming bystander cells for more efficient bacterial infection." (PMID 34099666, 2021). "Having shown that Salmonella infection elicits a strong downregulation of E2F1 in vitro with important consequences for the outcome and dissemination of infection, we examined whether E2F1 regulation could be observed in vivo." (PMID 34099666, 2021). "Considering the magnitude of E2F1 downregulation and its specificity during Salmonella infection, we pondered whether it could impact the infection process." (PMID 34099666, 2021). "Together, these results show that the decrease of E2F1 expression upon Salmonella infection that ensues from activation of the ER-stress response pathway is required to sustain a productive bacterial replication inside host cells, as well as to promote infection of bystander cells." (PMID 34099666, 2021). "To investigate the importance of E2F1 downregulation to the miRNA expression changes occurring during Salmonella infection, we have performed a comparative analysis of miRNA expression datasets obtained from small RNA sequencing of Salmonella-infected HeLa cells and E2F1 knockdown cells." (PMID 34099666, 2021). "To elucidate the contribution of the ER-stress response to the decrease of E2F1 and miRNA expression during Salmonella infection, we first examined whether this pathway is activated upon Salmonella infection and/or upon treatment of naive cells with the secretome of Salmonella-infected cells." (PMID 34099666, 2021). "Overall, our data indicate that IRE1 activation upon Salmonella infection or secretome treatment leads to JNK activation, which phosphorylates and thus inactivates E2F1." (PMID 34099666, 2021). "Following IRE1 activation upon Salmonella infection/secretome treatment, our data support a model in which the JNK pathway is activated by IRE1 leading to phosphorylation of E2F1, among other targets." (PMID 34099666, 2021). "Of note, knockdown of ATF6 or PERK did not affect E2F1 downregulation elicited by Salmonella infection or secretome treatment, indicating that neither of these branches contributes to E2F1 regulation in these biological settings." (PMID 34099666, 2021). "It is conceivable that for miR-34a and miR-125a-5p, miRNAs that are not significantly changed in E2F1 knockdown cells but that are downregulated during Salmonella infection and secretome treatment, there is a contribution of IRE1-mediated degradation." (PMID 34099666, 2021). "Conversely, preventing E2F1 downregulation by blocking the activation of the IRE1 pathway (KIRA6 treatment) inhibited Salmonella infection and thwarted the increase in Salmonella infection elicited by pre-treatment with the secretome of Salmonella-infected cells." (PMID 34099666, 2021).
SCC of the tongue (1 paper, 2008). "Therefore, overexpression of CDC6 and CDT1 in SCC of the tongue may be due, at least in part, to an E2F-1 to -3 mediated effect." (PMID 19116018, 2008).
scrapie (1 paper, 2010). A fatal disease of the nervous system in sheep and goats, characterized by pruritus, debility, and locomotor incoordination. "A recent study of microRNA signature of prion-induced neurodegeneration has shown that EGR1, E2F1 and MAZ might be also implicated in the putative deregulation of immune response related genes by miRNAs via modulation of transcriptional regulators in scrapie-infected mice." (PMID 20405009, 2010).